CDK6 (cyclin dependent kinase 6)
Diseases named in the same sentence as CDK6 in open-access papers (continued):
Sharing a sentence is not in itself a finding about the gene and the disease.
melanoma (continued). "Genomic profiling of 23 available subjects also identified gene amplifications of cell cycle regulators (Cyclin D1, CDK4, or CDK6), fibroblast growth factors (FGF19, FGF3, and FGF4) and EMSY (a DNA repair inactivating gene) uniquely clustered in acral melanoma subjects in the study." (PMID 30642373, 2019). "Moreover, the combination of CDK6 inhibition and a mitogen-activated protein kinase may result in cell cycle arrest and increasing in apoptosis a NRAS mutant melanoma mouse model." (PMID 36619863, 2022). "Importantly tumor nodules completely regressed thereafter and were no longer visible or palpable 9 days after injection of melanoma cells that had either decreased CDK4 or CDK6 expression in contrast to the controls which rapidly increased in volume." (PMID 30858922, 2019). "Furthermore, we verified key gene expression with mRNA levels after treatment with VB1 in melanoma cells, which indicated that the P21, PUMA and GADD45A expression was significantly upregulated and that the expression of MCM6, CDK1, CDK6, CYCE and CYCA was significantly downregulated." (PMID 30400954, 2018). "When we crossed this list with the list of down regulated mRNAs in miR-377-expressing melanoma cells, we found 4 putative transcripts with miR-377-binding sites: E2F3 (a putative target of miR-377 in 6 out of 10 software), MAP3K7 (in 4 out of 10), KRAS (in 5 out of 10) and CDK6 (in 5 out of 10)." (PMID 25889255, 2015). "Furthermore, it reinforces that CDK4, rather than CDK6 (Shennan etal., 2000), is the critical kinase in melanoma." (PMID 18843795, 2008). "WGS studies have suggested that TWT melanomas, commonly of the AM subtype, are more likely to have focal amplifications of CCND1, MDM2, KIT, and KRAS, as well as CDK4 and CDK6, than non-TWT melanomas." (PMID 39858514, 2025). "Silencing CDK6 and FSCN1, but not AXL, significantly reduced melanoma cell proliferation." (PMID 41286309, 2025).
glioblastoma (59 papers, 2008 to 2025). The most malignant astrocytic tumor (WHO grade IV). "Transfection of microRNA-124 or microRNA-137 also induced G1 cell cycle arrest in U251 and SF6969 glioblastoma multiforme cells, which was associated with decreased expression of cyclin-dependent kinase 6 and phosphorylated retinoblastoma (pSer 807/811) proteins." (PMID 18577219, 2008). "Moreover, miR-124, which is transported by MSC-EVs, exerts an inhibitory effect on glioblastoma (GBM) migration by targeting CDK6, while also enhancing the susceptibility of GBM cells to temozolomide (TMZ) therapy." (PMID 38164177, 2024). "Core glioblastoma stem cells (GSC)-associated genes (such as CDK6 and SOX2) were up-regulated by recurrent SEs, thereby maintaining GSC properties and promoting the malignancy of glioblastoma." (PMID 39090713, 2024). "Further research revealed that 5-Demethylnobiletin induces cell cycle arrest at the G0/G1 phase in glioblastoma cells by downregulating Cyclin D1 and CDK6 expression levels." (PMID 37139163, 2023). "Wharton’s jelly-derived MSC (WJ-MSC)-derived exosomes transfected with miR-124 have been confirmed to sensitize glioblastoma cells to TMZ and inhibit glioblastoma cell proliferation and migration of by directly targeting CDK6 in vitro." (PMID 36100944, 2022). "Topotecan, a United States Food and Drug Administration-approved anti-glioblastoma drug, can reduce overall cell SUMOylation, CDK6, and HIF-1α levels and regulate the cell cycle, but the specific target is not clear." (PMID 33898460, 2021). "miR-340 was found to specifically target the 3' UTRs of CDK6, cyclin-D1, and cyclin-D2, leading to the arrest of glioblastoma multiforme (GBM) cells in the G0/G1 cell cycle phase 42." (PMID 33390846, 2021). "CKD3 and CDK6 inhibitors have shown efficacy in glioblastoma models and are being studied in clinical trials in glioblastoma patients (NCT02345824)." (PMID 33396284, 2020). "Further, mRNA products of CDK4, CDK6 and α-tubulin were significantly higher in glioblastoma than those in normal tissues, and these results were significantly correlated to pathological grades and clinical prognosis via analyzing TCGA and CGGA databases." (PMID 32860670, 2020). "Newer-generation CDK4 and CDK6 inhibitors have shown promising brain penetration and efficacy signals in brain metastases, and the results of glioblastoma trials are eagerly awaited." (PMID 33396284, 2020). "The downregulation of CDK6 significantly inhibited cell viability and migration in human glioblastoma." (PMID 32860670, 2020). "Next, we determined that Presenilin1 inhibited the growth and proliferation of glioblastoma cells by downregulating CDK6, C-myc and Cyclin D1 to arrest the cell cycle at the G1/S phase." (PMID 32046730, 2020). "In the present study, we report the potential role of CDK6 and its possible regulatory mechanism in glioblastoma." (PMID 23594394, 2013). "The CDK6 gene is frequently amplified or overexpressed in a variety of human tumors such as glioblastoma and human lymphoid malignancies." (PMID 23300567, 2012). "Additionally, SAE1 correlates with glioblastoma grade and affects cell cycle regulators, while SUMOylation stabilizes CDK6, driving the G1/S transition." (PMID 41659205, 2025).
glioblastoma (continued). "Glioblastoma is characterized by a high frequency of CDK4/CDK6 pathway dysregulation." (PMID 36900358, 2023). "Similar results were obtained from other groups, who demonstrated that AGK2 induces growth inhibition in the sub-G0 (pre-G1) phase in glioblastoma cells and in the sub-G0 and G1 phases in cervical cancer cells which were mediated by the decrease in cyclin D1, Cdk4 and Cdk6 expression." (PMID 35406775, 2022). "In addition, UBE2I promotes the SUMOylation of CDK6 in glioblastoma and promotes tumor cell development by regulating the cell cycle." (PMID 33898460, 2021). "However, CDK2/CDK4 and CDK6 expressions were negatively correlated with immune infiltration in glioblastomas and skin cutaneous melanomas." (PMID 33668805, 2021). "Studies showed that CDK6, as an oncogene, was required for glioblastoma proliferation." (PMID 32860670, 2020). "The inhibitors of CDK-4 and CDK-6 have shown promise in glioblastoma treatment." (PMID 30038719, 2018). "miR-340 inhibits glioblastoma cell proliferation by suppressing CDK6, cyclin-D1 and cyclin-D241." (PMID 27686215, 2016). "Similarly, as a novel method for the treatment of glioblastoma multiforme, WJ-MSCs’ exosomes were used to deliver miR-124, which reduced the expression of CDK6 and enhanced chemosensitivity to temozolomide, along with decreasing the migration of glioblastoma multiforme cells." (PMID 37440921, 2023). "However, direct regulation was only validated for CDK6 in glioblastoma multiforme." (PMID 34937878, 2022). "Cyclin-dependent kinases, CDK4 and CDK6, are essential in regulating the cell cycle, which is disrupted in cancers like isocitrate dehydrogenase wild-type glioblastoma (GBM)." (PMID 36033522, 2022). "In line with our findings, previous studies have reported that inhibitors of CDK6 mediated mTOR activation while combined therapy of an mTOR inhibitor and a CDK6 inhibitor synergized to achieve enhanced inhibition of tumor growth in glioblastoma, head and neck and pancreatic cancers." (PMID 34572040, 2021). "Through suppression of several oncogenes including p-AKT, EZH2, XIAP, CDK6, cyclin-D1 and cyclin-D2, overexpression of miR-340 inhibits cancer cell proliferation, migration and invasion, induces apoptosis and autophagy in glioblastoma and miR-340 is a marker for glioblastoma diagnosis and prognosis." (PMID 27036021, 2016). "CDK4 was focused as a target during in silico study because it is reported to be significantly more elevated in glioblastoma than CDK2 and CDK6." (PMID 39650055, 2024). "In glioblastoma, overexpression of CDK2, CDK4, and CDK6 is frequently observed, underscoring their critical role in driving astrocytic tumorigenesis and glioma progression." (PMID 39650055, 2024). "In glioblastoma stem cells isolated from PDX mouse models originally derived from human tumor samples, a subset of super-enhancers at the loci of critical genes, such as CDK6, SOX2, EGFR and BRD4, are shared by the majority of human glioblastoma stem cells." (PMID 38135679, 2023). "Based on what is known regarding the regulation of E2F transcription factors, we decided to test if the previously identified Msi1 direct targets CDK6, CDKN1A/p21, CDKN1B/p27 affect E2F2 and E2F8 levels in glioblastoma cells." (PMID 33804958, 2021). "We also mined the clinical data of glioblastoma cohorts in TCGA, PanCancer Atlas and found that alterations in mTOR, STAT3, and CDK6 constituted 5% of the genetic alteration occurring in GBM patients." (PMID 34572040, 2021). "Moreover, miR-34a could repress CDK6 protein expression in different cancer cells suppressing cell proliferation and promoting apoptosis in nasopharyngeal cancer, cervical cancer and glioblastoma." (PMID 33796457, 2021).
glioblastoma (continued). "Consequently, downregulation of the PI3K-Akt/NF-κB/mTOR, STAT3, and CDK6 signaling pathways was reportedly used to abrogate GBM oncogenic properties and re-sensitized aggressive glioblastomas to chemotherapy." (PMID 34572040, 2021). "CDK4 and CDK6 activate FOXM1, and FGFR1 appears to be involved in FOXM1 expression since silencing of FGFR1 in glioblastoma cells resulted in downregulation of FOXM1." (PMID 32976773, 2020). "The CDK4/CDK6 and TUBA1C mRNA levels were higher in glioblastomas than those in normal brain tissues." (PMID 32860670, 2020). "In glioblastomas, the Rb protein is usually inhibited either by a Rb gene deletion or by CDK4 and CDK6 gene amplification, thus promoting tumor cell proliferation." (PMID 32650495, 2020). "CDK6 is a validated target in the treatment of Glioblastoma, a kind of brain tumor that is characterized by a high frequency of CDKN2A/CCND2/CDK4/CDK6 pathway dysregulation." (PMID 32858868, 2020). "Expression levels of Cyclin-Dependent Kinase (CDK-1, CDK-2, and CDK-6) were also significantly down-regulated in U87TRAF3IP2KD cells (-9.3, -2.4, and -2.1, respectively), indicating that silencing TRAF3IP2 affects glioblastoma cell cycle progression." (PMID 30038719, 2018). "Regarding the first signature network component, hsa-mir-137, hsa-mir-330, hsa-mir-149, hsa-mir-107, hsa-mir-181b were among the miRNAs whose experimentally validated targets (such as CTBP1, CDC42, CDK6, E2F1, VEGFA, AKT1, KAT2B) affect the pathways which play a crucial role in glioblastoma biology." (PMID 28045122, 2017). "Considering that the pRB signaling is inhibited by kinase activities of the CDK4/CDK6 and Cyclin D complex, the inactivation of CDK4/6 could be a novel anti-glioblastoma treatment option for GBM patients with aberrant expression of pRB." (PMID 33113890, 2020). "In glioblastoma multiform, the response to PD0332991 failed to correlate with the level of CDK6 or 4 expression." (PMID 28472136, 2017).
bladder cancer (56 papers, 2012 to 2025). "The m6A binding and stabilization of CDK6 by IGF2BP3 represents a potential molecular mechanism underlying cisplatin resistance in bladder cancer cells." (PMID 40083693, 2025). "CDK6 has been found as a target of several miRNAs, including miRNA-195, miRNA-29c, miRNA-218, miRNA-504, and miR-6883, and linked to bladder cancer, colon cancer, oral verrucous carcinoma, and medulloblastoma." (PMID 30718521, 2019). "In this analysis, we found an association of CDK6 with DFS of bladder cancer patients (Supplement )." (PMID 31828101, 2019). "CDK6 controls the cell cycle, and dysregulation of CDK6 is associated with bladder cancer progression." (PMID 24069260, 2013). "Gain-of-function and loss-of-function studies showed that GAS5 inhibits bladder cancer cell proliferation, at least in part, by regulating CDK6 expression." (PMID 24069260, 2013). "In addition, drug susceptibility assays had shown that knockdown of CDK6 can increase cisplatin chemotherapy sensitivity in bladder cancer cells." (PMID 40083693, 2025). "This indicates that FTO exhibits an oncogenic role via the FTO/miR-576/CDK6 pathways in bladder cancer and could be a potential diagnostic or prognostic biomarker for bladder cancer." (PMID 34725345, 2021). "CCK-8 assay results showed that knockdown of CDK6 reversed IGF2BP3 induced proliferation in bladder cancer cells." (PMID 40083693, 2025). "Our findings demonstrated that IGF2BP3 enhances resistance to cisplatin in bladder cancer cells by interacting with CDK6, thereby impeding the cytotoxic effects of cisplatin." (PMID 40083693, 2025). "This study demonstrates that Insulin-like growth factor 2 mRNA binding protein 3 (IGF2BP3) promotes bladder cancer (BCa) proliferation and chemoresistance in an m6A-dependent manner by directly stabilizing Cyclin-dependent Kinase 6 (CDK6) mRNA." (PMID 40959282, 2025). "Results demonstrated a significant correlation between overexpression of CDK6 and poor survival prognosis for patients with bladder cancer (P=0.039), while other regulators within this pathway did not exhibit any impact on patient survival outcomes." (PMID 40083693, 2025). "To verify the role of CDK6 in bladder cancer, we transfected small interfering RNA (siCDK6) or control (SCR) plasmids of CDK6 into T24 and UMUC3 cells." (PMID 40083693, 2025). "The IHC analysis of TMA from bladder cancer revealed a significant positive correlation between the expression of CDK6 and IGF2BP3." (PMID 40083693, 2025). "In conclusion, our study underscores the pivotal role of IGF2BP3 in driving cisplatin resistance in bladder cancer, primarily by stabilizing CDK6 mRNA in an m6A-dependent manner." (PMID 40083693, 2025). "To evaluate cell proliferation when CDK6 interacted with IGF2BP3 in bladder cancer, we transfected CDK6 small interfering RNA (siCDK6) or control (SCR) into over-expressed IGF2BP3 cells." (PMID 40083693, 2025). "This interaction enhances the stability of CDK6 mRNA, thereby regulating cell cycle progression and promoting bladder cancer cell proliferation." (PMID 40083693, 2025). "We conducted a bioinformatics analysis and immunohistochemistry to explore the biological landscape of CDK6 in tumors, with a particular focus on bladder cancer." (PMID 39310261, 2024). "A similar mechanistic mode has been proposed in bladder carcinoma where circular RNA TCF25 serves as a molecular sponge for miR-107 to upregulate CDK6 expression and promote proliferation." (PMID 37744274, 2023). "In the same year, a study by Zhou found that FTO facilitated bladder cancer progression via the FTO/miR-576/cyclin-dependent kinase 6 (CDK6) axis." (PMID 35628623, 2022). "The effects of different CDK4/6 inhibitors were tested on bladder carcinoma cell lines with different CDK6 expression levels." (PMID 35463324, 2022). "In bladder cancer cells, miR-106a inhibits the expression of cyclin D1 and CDK6 and enhances the p21CIP1/WAF1 pathway, which arrests the cell cycle at the G1 phase." (PMID 36233210, 2022).